DHX9 (DExH-box helicase 9)
Diseases named in the same sentence as DHX9 in open-access papers (continued):
Sharing a sentence is not in itself a finding about the gene and the disease.
hepatocellular carcinoma (22 papers, 2018 to 2025). A malignant tumor that arises from hepatocytes. "The dhx9 gene locus at 1q25 is frequently mutated in breast and prostate neoplasms and RHA overexpression was dubbed a biomarker of malignancies including lung and ovarian cancer, hepatocellular carcinoma, glioblastoma, chemo resistant leukemia, and osteosarcoma exhibiting high metastatic ability." (PMID 37386121, 2023). "This study identified DExH-Box Helicase 9 as a key protein through proteomics screening, revealing its high expression in hepatocellular carcinoma tissues and its correlation with poor patient prognosis." (PMID 39941810, 2025). "Further experiments showed that DExH-Box Helicase 9 regulates the AKT signaling pathway, and animal studies confirmed that DExH-Box Helicase 9 knockdown inhibits hepatocellular carcinoma growth, whereas its overexpression reduces Haprolid’s efficacy." (PMID 39941810, 2025). "Studies have shown that the expression level of DHX9 mRNA was significantly increased in a variety of cancers, such as ewing sarcoma, colorectal cancer, and hepatocellular carcinoma." (PMID 37305700, 2023). "Overall, we conclude that UHRF2 modulates the DHX9 protein levels via the ubiquitin-proteasome pathway in HBV-negative hepatoma cells." (PMID 36690646, 2023). "LNC-UCID enhances the expression of CDK6 by binding to DHX9 in hepatocellular carcinoma, and promotes G1/S transformation and the growth of hepatocellular carcinoma." (PMID 35410446, 2022). "Recently, research results of Yu show that unregulated DHX9 contributing to downregulation of cSMARCA5 mediates the promotion of growth, aggression and metastasis of hepatocellular carcinoma (HCC)." (PMID 32467668, 2020). "DHX9, an abundant nuclear RNA helicase, contributes to the downregulation of circSMARCA5 in hepatocellular carcinoma by binding to inverted-repeat Alu elements." (PMID 30312173, 2018). "DHX9 is overexpressed in a number of cancers, including small cell lung cancer, colorectal cancer, and hepatocellular carcinoma, suggesting that DHX9 may represent a novel target for cancer therapy." (PMID 40716747, 2025). "Therefore, it is excluded that upregulation of UHRF2 simultaneously promotes the development of hepatocellular carcinoma independently of DHX9." (PMID 36690646, 2023). "High expression of DHX9 promotes the growth and metastasis of hepatocellular carcinoma." (PMID 35600388, 2022). "Our hypothesis is in agreement with the data reported by Yu and colleagues that demonstrated how circSMARCA5 biogenesis is controlled by DHX9 in hepatocellular carcinoma." (PMID 33562358, 2021). "To test whether DHX9 regulate the expression of circDLC1, we examined the expression of circDLC1 in hepatoma cell lines after silencing DHX9." (PMID 33391541, 2021). "RIP assay with DHX9 antibody showed high binding probability of DHX9 at I13RC and I16RC in hepatocellular carcinoma cells." (PMID 41369410, 2025). "DHX9 knockdown increased the protein and mRNA levels of CDK6, which consequently resulting in hepatocellular carcinoma development." (PMID 35600388, 2022). "DHX9 expression is upregulated in hepatocellular carcinoma (HCC) tissues." (PMID 34676915, 2021). "At the same time, the literature reports downregulation of DHX9 expression in non-HBV hepatocellular carcinoma, indirectly affirming our conclusion." (PMID 36690646, 2023). "Similarly, the DHX9-NONO-SFPQ complex regulates the oncogenic splicing switch of BIN1 in hepatocellular carcinoma." (PMID 39048555, 2024). "Previously, many studies have found that DHX9, DHX15, DDX24, DHX29, etc. are widely involved in tumor progression through various pathways, however, the role of DHX37, as an important member of the DEAD/H-box RNA helicase family, in hepatocellular carcinoma progression has been less studied." (PMID 37958405, 2023).
hepatocellular carcinoma (continued). "DHX9, as an NTP-dependent helicase protein, plays a vital role in varieties of cellular processes, and aberrant DHX9 expression participates in multiple human diseases including various cancers, e.g. colorectal cancer (CRC), hepatocellular carcinoma, and prostate cancer." (PMID 36578944, 2022). "In a similar vein, DHX9 can also mediate CDK6 downregulation, thereby supporting the helicase’s tumor suppressive functions that are compromised in hepatocellular carcinoma (HCC) due to the overexpressed long noncoding (lnc) RNA lnc-UCID." (PMID 33437516, 2020). "DHX9, an NTP‐dependent RNA helicase, is closely associated with the proliferation and metastasis of some tumor cells and the prognosis of patients, but its role in hepatocellular carcinoma (HCC) is not well‐known." (PMID 34676915, 2021).
colorectal cancer (21 papers, 2020 to 2025). A primary or metastatic malignant neoplasm that affects the colon or rectum. "Notably, in lung, breast, renal, and colorectal cancer, and glioma, DHX9 has been associated with promoting cell proliferation and migration." (PMID 39941810, 2025). "Taken together, we demonstrated and linked the functional role of DHX9 phosphorylation to oncogenic circCCDC66 expression during the development of resistance to oxaliplatin, providing a mechanistic insight for the development of therapeutic strategies to recurring/chemoresistant colorectal cancer." (PMID 32187976, 2020). "DHX9 has been reported to inhibit EMT in A549 lung adenocarcinoma cells, is overexpressed in several cancer types, including lung, breast, and colorectal cancer, and is implicated in the TGFβ pathway." (PMID 39342995, 2024). "Previous study have proved that DHX9 contributes to the malignant phenotypes of colorectal cancer by activating NF-κB signaling pathway." (PMID 38041141, 2023). "It was further confirmed that DHX9 was highly expressed in breast cancer, lung cancer, sarcoma, colorectal cancer and brain tumor." (PMID 37214432, 2023). "LINC00460/DHX9/IGF2BP2 complex stimulates colorectal cancer proliferation and metastasis by interacting with IGF2BP2 and regulating HMGA1 mRNA stability by m6A modification." (PMID 37744330, 2023). "Secondly, DHX9 is overexpressed in many tumors including lung and colorectal cancers and for this reason, it has recently been proposed as a potential therapeutic target." (PMID 33437516, 2020). "Recently, it has been discovered that DHX9 phosphorylation can promote upregulation of oncogenic circCCDC66, which correlates with colorectal cancer (CRC) growth, invasion and metastasis." (PMID 33437516, 2020). "In addition, DHX9 induced the malignant phenotype of colorectal cancer by activating NF-κB signaling pathway." (PMID 37903782, 2023). "Moreover, DHX9 plays an important role in promoting the metastasis of colorectal cancer." (PMID 35280928, 2021). "This confirms the potential of LINRIS-IGF2BP2-MYC axis for colorectal cancer targeted therapy; LncRNA LINC00460 interacts with IGF2BP2 and DHX9 to form the LINC00460/DHX9/IGF2BP2 complex." (PMID 35070987, 2021).
breast carcinoma (19 papers, 2015 to 2025). "The study further proposed that the upregulation of AK023948 and DHX9 may play a role in breast cancer progression, as DHX9 associates with poorer survival in breast cancer, highlighting lncRNAs as potential therapeutic targets." (PMID 40650785, 2025). "DHX9 truncation mutants have been identified in individuals with high risk of breast cancer, suggesting variants of DHX9 may promote oncogenesis." (PMID 39620586, 2025). "Finally, AK023948 is upregulated in breast cancer; interrogation of TCGA data set indicates that upregulation of DHX9 in breast cancer is associated with poor survival." (PMID 28176758, 2017). "However, whether DHX9 regulates autophagy deficiency in breast cancer (BC) remains unknown." (PMID 40659605, 2025). "Together, these results reveal that ADAR1 and DHX9 redundantly suppress PKR activation in ADAR1-independent breast cancer cell lines." (PMID 38530197, 2024). "The knockout of DHX9 had the same effects on EMT as DHX9 knockdown in liver cancer, lung cancer, breast cancer, and renal cell carcinoma cells." (PMID 37214432, 2023). "Herein, we found that the S87 site of DHX9 between the two DSRM domains of DHX9 demonstrated a higher phosphorylation level in breast cancer, ovarian cancer and colon cancer than those in normal tissues." (PMID 37214432, 2023). "Among them were several nuclear proteins, which have previously been identified in BRCA1-deficient breast carcinomas (TOP1, SMC3, SSRP1 and DHX9)." (PMID 27566577, 2016). "Notably, previous studies have indicated that DHX9 knockdown in breast cancer attenuates the AKT pathway, whereas its overexpression amplifies it." (PMID 39941810, 2025). "Using shRNAs, we knocked down DHX9 in two ADAR1-independent breast cancer lines, MCF-7 and SK-BR-3." (PMID 38530197, 2024). "The similarities between ADAR1 and DHX9 led us to further study the role of DHX9 in breast cancer." (PMID 38530197, 2024). "DHX9 expression is strongly correlated with ADAR1-p110 expression in breast cancer." (PMID 38530197, 2024). "As for protein expression levels, CPTAC database results showed that DHX9 total protein expression in breast cancer, ovarian cancer, colon cancer, UCEC, and LUAD tissues was higher than that in normal tissues, but the expression of ccRCC was lower than that of normal tissues." (PMID 37214432, 2023). "In addition, by analyzing the data from the TCGA and GEO databases, we found that DHX9 was significantly upregulated in breast cancer, especially in the TNBC subtype, and was related to the poor overall survival of patients." (PMID 36038948, 2022). "Furthermore, high expression of DHX9 was significantly associated with poor RFS (relapse-free survival), DMFS (distant metastasis-free survival), and PPS (post-progression survival) in patients with breast cancer." (PMID 37214432, 2023). "LncRNA 01016 suppresses DHX9 proteasomal degradation, increases DHX9 expression, activates the PI3K/Akt signaling pathway, and improves breast cancer cell migration." (PMID 40703656, 2025). "Together, these findings show that DHX9 is essential in breast cancer cell lines and that in some ADAR1-dependent cell lines, DHX9 suppresses PKR activation." (PMID 38530197, 2024). "We have identified three highly connected modules, EED, DHX9, and AURKA, which are extremely activated in TNBC tumors compared to both normal tissues and other breast cancer subtypes." (PMID 31134131, 2019). "As previously discussed, DHX9 interacts with BRCA1 to coordinate HR and maintain genomic integrity, however, overexpression of a DHX9 peptide fragment containing the region for BRCA1 interaction was shown to inhibit BRCA1 activity in breast epithelial cells and promote breast cancer progression." (PMID 33437516, 2020).
breast carcinoma (continued). "Using an engineered metastatic niche, we identified a 9‐gene signature (Dhx9, Dusp12, Fhl1, Ifitm1, Ndufs1, Pja2, Slc1a3, Soga1, Spon2) that successfully delineated metastatic breast cancer from nonmetastatic breast cancers including an invasive cell line without metastatic potential." (PMID 38193115, 2024). "Furthermore, DHX9 was also upregulated in breast cancer cell lines as compared with non-malignant HMLE cells." (PMID 28176758, 2017).
viral infection (16 papers, 2013 to 2025). "Intriguingly, under conditions of viral infection or direct interferon stimulation, DHX9 uniquely associates with the ISG promoter region, facilitating STAT1-mediated transcription of a of ISGs67." (PMID 38594251, 2024). "A wealth of recent studies have implicated DHX9 in human diseases such as various cancers and viral infections, and there is evidence supporting the targeting of DHX9 in disease intervention." (PMID 27034008, 2016). "This study showed that during viral infection, the hDicer helicase binds to proteins that are involved in the antiviral response, such as DHX9, ADAR-1, and PKR kinase." (PMID 39695695, 2024). "We also performed subcellular fractionation separation experiments on HeLa cells stimulated with poly(I:C) or VSV, followed by Western blot analysis, and further confirmed the nucleus distribution of DHX9 in a steady state or upon viral infection." (PMID 36735791, 2023). "There were no developmental abnormalities for CD8+ T cells in the thymi and spleens after DHX9 deletion, while loss of DHX9 impairs the accumulation of CD8+ effector and memory T cells upon viral infection." (PMID 36735791, 2023). "Apart from components of the cellular stress granules, we also confirmed the colocalization of dsRNA (which were detected upon viral infection) in the DHX9 antiviral granules." (PMID 33952639, 2021). "Analysis of differential gene expression by gene set enrichment after combined knockdown of ADAR1 and DHX9 in MCF-7 revealed activation of multiple pathways involved in the innate response to viral infection and repression of several pathways involved in translation." (PMID 38530197, 2024). "Most of the DEAD/H-box RNA helicases are conserved, but DHX9 and RIG-I are genetically deficient in chickens, which may cause exacerbation of viral infections like influenza in chickens." (PMID 35583334, 2022). "The results indicate that knockdown of DHX9 enhanced FLuc expression from vMyx-FLuc expression at both early and late time points; however, at late time points, FLuc expression increased almost 10-fold compared to untreated virus infection alone or control siRNA transfection." (PMID 33952639, 2021). "The opposing roles of DHX9 in both pro-viral and anti-viral response suggests that there may be a tug-of-war between the host cell's attempts to combat viral infection and the viruses' attempts to hijack cellular machinery - a battle in which DHX9 appears to play a crucial part." (PMID 27034008, 2016). "Physiologically, NUP98 participates in bidirectional transport across NPCs, regulates gene expression in cooperation with DExH-Box helicase 9 (DHX9), and restricts viral infection." (PMID 39080077, 2024). "The retention of DHX9 in the nucleus also increased the number of GFP-positive virus-infected cells in the CRM1 siRNA-mediated knockdown cells, reflecting enhanced viral infection (GFP panels)." (PMID 37377603, 2023). "ATP-dependent RNA helicase A (also known as DHX9) has also been shown to negatively regulate circRNAs expression via a similar mechanism, while immune factors NF90/NF110 can promote circRNAs production by stabilizing intronic RNA pairs in viral infection." (PMID 34604256, 2021). "Our results also show that DHX9 antiviral granules are formed after viral infection but not by common nonviral cellular stress inducers." (PMID 33952639, 2021).
cervical cancer (15 papers, 2017 to 2025). A primary or metastatic malignant neoplasm involving the cervix. "LINC02962, also known as lnc-CCDST, was found to be significantly downregulated in cervical cancer tissues and bind to pre-carcinogenic DHX9 and E3 ubiquitin ligase MDM2, thereby affecting cervical cancer cell invasion and angiogenesis." (PMID 37928532, 2023). "In cervical cancer cells, the proto-oncogene DHX9 binds to the lncRNA lnc-CCDST and MDM2 to regulate cell invasion and angiogenesis." (PMID 35410446, 2022). "Lnc-CCDST inhibits the angiogenesis and migration by degrading the DHX9 expression and destructing the binding of MDM2 to DHX9 in cervical cancer." (PMID 36077731, 2022). "RIP assay using DHX9 antibody showed that intron 1 and intron 3 of LMO1 are significantly enriched, indicating that up-regulated DHX9 results in a decrease in circLMO1 in cervical cancer." (PMID 35321435, 2022). "DHX9 knockdown enhances circLMO1 expression in cervical cancer cells, while DHX9 overexpression down-regulates circLMO1 expression." (PMID 35321435, 2022). "The expression of DHX9 is up-regulated in cervical cancer tissue, which promotes the movement and angiogenesis of cervical cancer cells." (PMID 35280928, 2021). "For example, DHX9 was highly expressed in cervical cancer and promoted cell motility and angiogenesis." (PMID 34512155, 2021). "Lnc-cervical cancer DHX9 suppressive transcript (lnc-CCDST) binds DHX9, acts as a scaffold to enhance MDM2-DHX9 binding and thus induces DHX9 degradation." (PMID 33437516, 2020). "In cervical cancer (CC) cells, lnc-CCDST is downregulated via the human papillomavirus-encoded E6 and E7 oncoproteins, allowing DHX9 to accumulate and result in enhanced invasion and angiogenesis." (PMID 33437516, 2020). "For example, the lncRNA CCDST (cervical cancer DExH-box helicase 9 suppressive transcript) acts as a scaffold between DHX9 (DExH-box helicase 9) and MDM2 to promote the degradation of DHX9." (PMID 31248165, 2019). "Knockdown of DHX9 in a representative panel of human cancer cell lines, including multiple myeloma, osteosarcoma, and breast, lung, and cervical cancer cells, demonstrated that DHX9 suppression was detrimental in the majority of cancer cells." (PMID 28427210, 2017). "Furthermore, VDAC1 has been shown to prevent the progression of HPV-induced cervical cancer and DHX9–lncRNA–MDM2 interactions regulate tumor cell invasion and the angiogenesis of CESC." (PMID 36900213, 2023). "Besides, a lncRNA, named lnc‐CCDST, has been reported to promote the degradation of DExH‐box helicase 9 (DHX9) by promoting the formation of the E3 ubiquitin ligase mouse double minute 2 homologue (MDM2)/DHX9 complex in cervical cancer." (PMID 36578176, 2023). "In this study, we showed that DHX9 expression in cervical cancer tissues is up-regulated." (PMID 35321435, 2022). "High-risk human papillomavirus (HPV) impairs the interaction between MDM2 and DHX9 and the degradation of DHX9 by inhibiting the expression of lnc-CCDST, thereby promoting the movement and angiogenesis of cervical cancer." (PMID 36338707, 2022). "E6 and E7 downregulated expression of cervical cancer DHX9 suppressive transcript (CCDST) lncRNA, which resulted in increased DExH-box helicase 9 (DHX9) protein levels, thereby accelerating cell mobility and angiogenesis." (PMID 34361112, 2021).